RNU5F-1 (RNA, U5F small nuclear 1)
Synonyms: RNU5F; U5F
Gene: Small nuclear RNA gene on chromosome 1 (44,721,785 to 44,721,902, reverse strand). Ensembl gene ENSG00000199377.
Gene Ontology:
Biological process: formation of quadruple SL/U4/U5/U6 snRNP; spliceosomal tri-snRNP complex assembly
Cellular component: U4/U6 x U5 tri-snRNP complex; U5 snRNP
Diseases named in the same sentence as RNU5F-1 in open-access papers:
RNU5F-1 is named in the same sentence as 1 disease in open-access papers, as found by Europe PMC text mining. Sharing a sentence is not in itself a finding about the gene and the disease.
RNU5F-1 shares sentences with these, for which no sentence is quoted: pulmonary diseases (1 paper).